MMP12 (matrix metallopeptidase 12)
Diseases named in the same sentence as MMP12 in open-access papers (continued):
Sharing a sentence is not in itself a finding about the gene and the disease.
cancer (continued). "Ultimately, the reprogrammed macrophages secrete MMP12, which coordinates the invasion of cancer cells into nerves." (PMID 40985319, 2025). "PNI‐specific mechanism: We demonstrated that SRC‐1 reprogrammed TAMs to secrete MMP12, directly facilitating cancer cell invasion along the nerves." (PMID 40985319, 2025). "The expression patterns of genes associated with high-risk signatures, namely MMP1, MMP12, and TIMP1, indicate their presence in a subset of macrophages, endothelial cells, and cancer-associated fibroblasts (CAFs)." (PMID 40362553, 2025). "MMP12 is one of the MMPs predominantly expressed by macrophages, and elevated MMP12 expression is found in various cancers." (PMID 41321310, 2025). "Matrix metalloproteinases are key regulators of invasion and microenvironment remodeling, and among them, matrix metalloproteinase-12 (MMP12) is a particularly attractive candidate whose network-level effects in cancer are still poorly defined." (PMID 41465234, 2025). "Critically, most existing studies often evaluate MMP12 inhibition solely at the enzymatic level, overlooking its broader cellular impacts and the system-level mechanisms by which it influences cancer progression." (PMID 41465234, 2025). "The connectivity landscape of MMP12 and its downstream targets highlighted its convergence on major cancer signaling axes, including ECM remodeling, PI3K-AKT, and cytokine signaling." (PMID 41465234, 2025). "Our study underscores the pivotal role of MMP12 as a cancer progressor in various malignancies, including cHL, making it a focal point for investigation and a potential therapeutic target." (PMID 39124881, 2024). "Our findings confirmed that MMP-12 can regulate lipid catabolism in CRPC cancer cells and affect their migration and invasion." (PMID 38511770, 2024). "MMP12 is a protein that has been reported to be highly expressed in various malignancies and plays a significant role in cancer progression." (PMID 39124881, 2024). "Several preclinical studies have demonstrated the potential benefits of targeting MMP12 in cancer therapy, and ongoing clinical trials are exploring the efficacy and safety of this strategy." (PMID 38560573, 2024). "Among these, guanylate cyclase, metallothionein, homeobox, olfactory receptor, prostaglandin-endoperoxide synthase 2, matrix metallopeptidase 12, and chrysrallin play roles in different types of pain, including visceral, neuropathic, and cancer-related pain." (PMID 38397842, 2024). "MMP12 inhibition can suppress cancer cell migration, invasion, and metastasis, making MMP12 an attractive therapeutic target in cancer treatment." (PMID 38560573, 2024). "For Mmp12 and Ltb4r1 genes, the high Mmp12 expression shows a trend toward better prognosis in H&N cancer (Human Protein Atlas)." (PMID 38686626, 2024). "Matrix metalloproteinase (MMP)-12 can degrade elastin as well as various extracellular matrix (ECM) components, which is associated with cancer progression." (PMID 38511770, 2024). "Since the previous results show that MMP12 is involved in the potential mechanisms of cancer through immune-related signaling pathways, we focused on the cells associated with TME." (PMID 37601247, 2023). "MMP12 was involved in cancer development and progression through two immune-related signaling pathways." (PMID 37601247, 2023). "The differential expression of MMP12 in cancer has received much attention, and its high expression has been reported several times." (PMID 37601247, 2023). "Despite its prevalence in inflammatory and cancer tissues, these results surmise that MMP12 was only detected in a few types of normal tissues, as well as the fast-remodelling tissue, but their expressions were relatively low." (PMID 36902078, 2023). "Transcriptome analysis revealed that CHRM3 knockdown significantly reduced an array of classic factors in cancer invasive growth including MMP1/MMP3/MMP10/MMP12 and CXCL1/CXCL5/CXCL8." (PMID 37744266, 2023).
cancer (continued). "In contrast, some reports have indicated that MMP12 expression is associated with better prognosis in human cancers, such as colon, gallbladder and HCC cancers." (PMID 35313071, 2022). "At present, a study has shown that the high expression of MMP12 in the serum of COAD patients leads to the impaired overall survival of cancer patients." (PMID 36387195, 2022). "MMP-12 is involved in the pro-tumorigenesis process through inhibiting cancer cell apoptosis and promoting cancer cell invasion and migration." (PMID 34758846, 2021). "Reportedly, the proteins Mmp12, Pparg, and Ptgs2 are related to digestive system disease and cancer." (PMID 31341536, 2019). "This grouping in cluster 2 features high expression of gene cluster B genes (MMP3, MMP10, MMP13, MMP1, and MMP12) in a pattern that is relatively unique among cancer types." (PMID 31200666, 2019). "We found that radiation induced the up-regulation of the chemokine CXCL12 and its receptor CXCR4, of the metalloproteinases 9 and 12 (MMP9 and MMP12), and of key transcription factors involved in the expression of genes related to migration of cancer cells." (PMID 30813636, 2019). "We found that IL-20 is able to stimulate the growth, migration, and function as an upstream mediator to enhance MMP-9, MMP-12, cathepsin K, and cathepsin G secretion in cancer cells." (PMID 29690863, 2018). "Several cancer-promoting genes were uperegulated (Ctgf, H19, Mmp12, Mybl1, Vnn1) while cancer inhibiting genes (Cish, Dkk4, Onecut1, Scara5, Socs3, Wif1) were suppressed." (PMID 26200659, 2015). "Taken together these data indicate that the role of MMP12 in human cancer is still much discussed and that it depends on its specific protein target and cleavage products." (PMID 25003596, 2014). "An overwhelming number of these downregulated gene sets, including those containing MMP-12 and MMP-13 (lower left) are associated with cancer." (PMID 22815700, 2012). "Some studies have suggested that the expression of MMP12 increases in various of cancers." (PMID 40244135, 2025). "MMP-12 has been found to be involved in the development and occurrence of malignant tumors." (PMID 38511770, 2024). "Therefore, the MMP12 gene represents a promising biomarker and therapeutic target for cancer management, with the potential to improve patient outcomes and survival rates." (PMID 38560573, 2024). "This up-regulation might be related to the general tendencies of MMPs in cancer, where MMP1 is significantly and almost universally up-regulated, and MMP3 and MMP12 show significant up-regulation in at least 10 types of cancer." (PMID 39596132, 2024). "Additionally, the protein-protein interaction network analysis in this study revealed an interaction between COL1A1 and MMP12, suggesting a potential functional connection between these two genes in the context of cancer progression." (PMID 39124881, 2024). "Therefore, the identification of MMP12 as a potential biomarker of cancer has significant clinical implications in cancer diagnosis, prognosis, and treatment." (PMID 38560573, 2024). "Matrix metallopeptidase 12 (MMP12) plays an essential role in a variety of cancers." (PMID 37601247, 2023). "Previous studies have shown that SNAI2 can induce the invasiveness of cancer cells; predictably, MMP12 might be involved in LUSC metastasis as a downstream gene of SNAI2, and this proposition was reinforced by ChIP-Seq data in the Cistrome Data Browser." (PMID 37601247, 2023). "MMP12 may be involved in cancer development by participating in immune-related signaling pathways and elevating the level of immune cell infiltration." (PMID 37601247, 2023). "Macrophages promote cancer invasion by secreting MMPs (MMP12, MMP8 and MMP14)." (PMID 37324952, 2023). "Additionally, MMP12 expression has been documented in tissues that undergo fast remodelling, such as the term placenta during human foetal development, and in several cancer tissues." (PMID 36902078, 2023).
cancer (continued). "Likewise, it is worth remarking that some MMPs have protective effects against cancer progression, for instance, MMP-12." (PMID 36213817, 2022). "Therefore, these compounds are predicted to inhibit growth and induce apoptosis of cancer cells through their interactions with MMP12, MMP13, CDK4, JAK3, VEGFR1, VEGFR2, and KCNA3." (PMID 36106139, 2022). "In contrast, MMP-12 concentrations were lower in cancer patients than in control subjects." (PMID 36213817, 2022). "MMP1, MMP3, and MMP12 were up-regulated in both inflammation and cancer." (PMID 35850748, 2022). "Conversely, our study population had advanced stages of the disease with low MMP-12 concentrations, which could facilitate cancer progression." (PMID 36213817, 2022). "However, in other types of cancers, upregulated MMP12 were reported to involve in short survival times." (PMID 33935718, 2021). "SOX6 directly activates transcription of aggrecan (Acan) and expression of MMP12 in cancer tissue." (PMID 34440750, 2021). "A panel of MMPs was analyzed in serum from PC patients—specifically, MMP-1, MMP-3, MMP-7, MMP-9, MMP-10, and MMP-12 were higher in cancer patients compared with healthy donors, showing good diagnostic accuracy, of which MMP-7 and MMP-12 achieved perfect discrimination." (PMID 30678058, 2019). "We first identified LIFR, PIK3R1, and MMP12 as novel prognostic biomarkers in this cancer." (PMID 31119098, 2019). "MMP13 and MMP12 are involved in carcinomas and inflammatory conditions." (PMID 30765775, 2019). "In the top 50 differentially expressed genes between cancer and normal tissues, three genes: neurotensin (NTS, red arrow), keratin 19 (KRT19) and matrix metallopeptidase 12 (MMP12) were screened out for their high expression in 2 cancer samples (c-13426 and c-13732)." (PMID 23418512, 2013). "It has been shown that increased expression of MMP12 may reflect a favorable prognosis in a few cancers." (PMID 15987457, 2005). "The MMP12 level can increase in various solid tumors, such as pancreatic, stomach, non-small cell lung, and liver cancers, and may be used as a new biomarker to predict the prognosis of different types of cancer." (PMID 40244135, 2025). "Therefore, we focused on the relationship between MMP-12 in cancer cells and adipocytes." (PMID 38511770, 2024). "However, there is few study on the interactions of MMP12 and TNFs in cancer development." (PMID 33935718, 2021). "Among the 22 investigated MMPs, seven genes (MMP2, MMP3, MMP10, MMP12, MMP14, MMP15, and MMP16) were upregulated in cancer, while MMP8 was downregulated." (PMID 41728806, 2026). "Total RNA-seq showed upregulation of 12 putative cancer-related genes near ISs, including MAGI1-AS1, HAS3, CASC8, BIRC2, and MMP12." (PMID 41157614, 2025). "Pathway enrichment of the eight prioritized genes placed the MMP12 network in ECM remodeling, immune/inflammatory regulation, and cancer signaling; each gene mapped to ≥1 significant pathway." (PMID 41465234, 2025). "MMP12, primarily expressed by macrophages, degrades extracellular matrix (ECM) components, thereby facilitating the migration and invasion of cancer cells." (PMID 39744560, 2025). "The MMP-12 protein was strongly expressed in cancer cells from the CRPC group, light MMP-12 staining was observed in the ADPC group, but the BPH samples exhibited very little staining." (PMID 38511770, 2024). "The MMP9, MMP12, MMP14, and MMP16 genes work synergistically to regulate processes such as tissue remodeling, wound healing, and cancer invasion." (PMID 39493455, 2024). "The prognostic value of high expression levels of MMP9, MMP12, MMP14, and MMP16 in various cancers, as indicated in this study, has also been reported in prior research." (PMID 39493455, 2024). "In this study, we found that the MMP-12 protein is highly expressed in human CRPC tissues and is positively correlated with an increase in the cancer Gleason score." (PMID 38511770, 2024).
cancer (continued). "mRNA expression levels of MMP-12, MMP-13, MMP-14, and MMP-19 in the cervical tissue of patients with cancer were greater than that observed in the control (p = 0.045, p = 0.025, p = 0.003, and p = 0.025, respectively)." (PMID 39247608, 2024). "According to our results, MMP-12 played important roles in the progression of CRPC by disrupting adipocyte maturation and regulating cancer migration and invasion via the modulation of autophagy and lipid catabolism pathways." (PMID 38511770, 2024). "The results showed that MMP2, MMP9, MMP12, and MMP16 promoter regions in KIRC samples were hypomethylated compared to non-cancer samples." (PMID 38560573, 2024). "Compared with the adjacent normal tissues and cancer tissues of patients taking atorvastatin, the expressions of MMP9, MMP12, CD36, and FABP4 in LUSC tissues increased significantly." (PMID 37978381, 2023). "Transcriptome analysis revealed that CHRM3 knockdown significantly reduced an array of classic factors involved in cancer invasive growth, including MMP1/MMP3/MMP10/MMP12 and CXCL1/CXCL5/CXCL8." (PMID 37744266, 2023). "According to our findings, the GPX3 expression is markedly decreased in most cancers, while MMP1 and MMP12 expression was distinctly upregulated in most types of tumors." (PMID 36081670, 2022). "We conducted pan-cancer assays based on TCGA datasets to investigate the putative roles of GPX3, MMP1, and MMP12 in malignancies." (PMID 36081670, 2022). "Based on this explanation, it was stated that the inhibition of the MMP12 and MMP13 activities correlated with the inhibition of cancer cell growth." (PMID 36106139, 2022). "In turn, cancer cell-derived signals triggered the expression of metalloproteinases (MMPs) including MMP2, MMP9, and MMP12 in SCs, promoting SCs to dissolve matrix." (PMID 32064233, 2020). "The protein levels of MMP12, MMP9 and TIMP3 are increased in cancer cells compared to controls after 48 h culture." (PMID 32171282, 2020). "Seven MMPs (MMP7, MMP11, MMP12, MMP13, MMP24, MMP27, and MMP28) had an AUC of greater than 0.95 for at least one cancer type." (PMID 31200666, 2019). "Previous studies reported that MMP-12, MMP-9, and cathepsin K accelerate extracellular matrix (ECM) degradation leading the invasion and metastasis of cancer cells." (PMID 29690863, 2018). "HCC patients with increased numbers of cancer stem cells also displayed an accumulation of a HIF-1α-driven SPP1+ macrophage subset characterized by the expression of MMPs (MMP9, MMP12, and MMP17), which may enhance cancer epithelial‒mesenchymal transition." (PMID 40721870, 2025). "To determine changes in cancer cell migration and invasion in the absence of MMP-12, we performed transwell assays with or without Matrigel coating in the upper chamber." (PMID 38511770, 2024). "Our data also showed that the migration and invasion of cancer cells were significantly reduced after MMP-12 was silenced, which indicated that MMP-12 may promote the migration and invasion of CRPC cells." (PMID 38511770, 2024). "Acting as a target to predict periodontal status, cancer, and TMD, reducing the levels of MMP12 in the oral environment may be a possible route to improving periodontal health." (PMID 36902078, 2023). "We also observed an increased expression of some metalloproteinases such as MMP14 and MMP2, which are known mediators of cancer invasion and a remarkable decrease of two metalloproteinases, MMP11 and MMP12, which are known to have a protective role against tumors." (PMID 34680461, 2021). "Despite the fact that several MMPs are involved in cancer cell migration, matrix crosslinking, and wound healing, a concrete role of MMP12 has not been elucidated in mechanotransduction involved during cutaneous wound repair." (PMID 34732729, 2021). "MMP3, MMP7, MMP12 and MMP14) are significantly up-regulated in at least 10 cancer types." (PMID 31200666, 2019). "IL-20 induces the expression of MMP9, MMP-12, RANKL, cathepsin K and cathepsin G in cancer cells." (PMID 29690863, 2018).
cancer (continued). "Many viral constructs have been designed to deliver new therapeutic information into cancer cells, but none of such viruses include an MMP12 construct." (PMID 25003596, 2014). "In addition to MMP12 (present study), MMP1, MMP13 and MMP28 have also been shown to promote invasion and metastasis in various cancers." (PMID 24885469, 2014). "The data showed that MMP-12 was present in all the tested cancer tissues, but not in the normal tissues." (PMID 24137407, 2013). "Some genes – such as metalloprotease MMP12 – display very favorable variation profile, being almost uniformly over-expressed in cancer and almost absent in norm." (PMID 19526064, 2009). "The number of mature adipocytes was increased in co-cultures with MMP-12-knockdown CRPC cells compared with MMP-12-expressing CRPC cells, suggesting that high expression of MMP-12 in cancer cells may interfere with the process of peripheral adipocyte maturation." (PMID 38511770, 2024). "Therefore, we studied whether MMP9, MMP12, FABP4, and CD36 genes are correlated with poor prognosis in various cancers." (PMID 37978381, 2023). "However, the protein levels of MMP9, MMP12 and TIMP3 are increased in cancer cells." (PMID 32171282, 2020). "In contrast, Mmp8 and Mmp12 have been ascribed a protective role in cancer, although this may be independent of their ability to shape the ECM." (PMID 31505876, 2019). "However, MMP-12 expression is actually increased in some cancer types including HNSCC and correlates with epithelial dedifferentiation and histological aggressiveness, suggesting that MMP-12 derived from cancer cells has a different role from that secreted by macrophages." (PMID 24531055, 2014). "Genes upregulated by >1.5‐fold in cancer tissues rather than in normal intestinal mucosae include Wnt signaling‐related genes such as Fzd1 (fold change [FC], 5.6), Myc (FC, 2.6), Ccnd1 (FC, 1.6), Mmp2 (FC, 10.4), Mmp7 (FC, 16.0), Mmp8 (FC, 12.9), Mmp12 (FC, 52.2), and Spp1 (FC, 149.3)." (PMID 35274815, 2022). "Results of this analysis showed a significant increase in MMP2, MMP9, MMP12, and MMP16 levels in KIRC patients across different cancer stages, races, genders, and age groups when compared to normal controls." (PMID 38560573, 2024). "There are now some selective MMP inhibitors developed for the treatment of the non-neoplastic disorders and cancer, such as MMP-13 inhibitors in OA, MMP-14 inhibitors in RA and cancer and MMP-12 inhibitors in COPD, all of which have been proven to be effective in animal models." (PMID 27455234, 2016). "From these findings, although MMP-12 is considered to be a marker for HNSCC aggressiveness, there are no studies showing whether MMP-12 inhibition can block cancer invasion and metastasis." (PMID 24531055, 2014). "Perhaps, although cortisol levels will be elevated in healthy subjects, MMP-12 concentrations would remain low in the absence of a stimulus such as neoplastic cell proliferation and hypoxia, which are TME conditions involved in angiogenesis during cancer's early stages." (PMID 36213817, 2022).